CYP2C19 (cytochrome P450 family 2 subfamily C member 19)
Diseases named in the same sentence as CYP2C19 in open-access papers (continued):
Sharing a sentence is not in itself a finding about the gene and the disease.
breast carcinoma (continued). "Given these contradictory findings, we used a large, publicly available dataset to investigate the association of CYP2C19*2 and CYP2C19*17 variants with breast cancer recurrence in both pre- and postmenopausal women treated with adjuvant tamoxifen therapy for ER-positive breast cancer." (PMID 28798474, 2017). "In a study of cancer recurrence in ER+ postmenopausal breast cancer cases, it was concluded that patients with a CYP2C19*2 allele may benefit more from tamoxifen therapy." (PMID 28391240, 2017). "There is evidence that the CYP2C19*3 variant may be associated with breast cancer risk in Chinese Han women." (PMID 28391240, 2017). "The decreased activity of CYP2C19 through haploinsufficiency might be related to an increase in breast cancer risk, potentially through life-long increased estrogen levels." (PMID 25466287, 2014). "Thus, CYP3A5*3 and CYP2C19*2 seem to be beneficial with regards to the risk of recurrence or to breast cancer-specific survival, respectively." (PMID 23346096, 2012). "Correspondingly, decreased activity of CYP2C19 through haploinsufficiency might potentially increase the risk of breast cancer." (PMID 22737080, 2012). "The variant CYP2C19*3 (rs57081121) which lead to a decreased activity of the CYP2C19 has been associated with increased risk in Asians and the variant CYP2C19*17 (rs12248560) causing an ultra rapid metabolizer phenotype leads to a decreased HRT-related breast cancer risk in Europeans." (PMID 23226154, 2012). "The identification of a recurrent deletion allele in CYP2C19, encoding an enzyme involved in estrogen metabolism and with an increased frequency in familial cases, further emphasizes the role of estrogen in breast cancer predisposition." (PMID 22737080, 2012). "This suggests that increased catabolism of estrogens by CYP2C19 may lead to decreased estrogen levels and therefore reduced breast cancer risk." (PMID 22737080, 2012). "However, some studies suggest that patients with the CYP2C19*2 heterozygous or homozygous genotypes may experience longer time-to-treatment failure and better overall breast cancer survival rates compared to those with the wild-type allele." (PMID 41295207, 2025). "Moreover, a comprehensive screening study on 250 Indian breast cancer patients confirmed the association of the CYP2C19*2 allele with disease outcomes, particularly highlighting the gene-dose effect of CYP2C19*2 in relation to an increased risk of adverse reactions." (PMID 39598531, 2024). "In contrast, the CYP2C19*17 allele, associated with ultra-rapid metabolism, leads to higher 4-OH-TAM levels, correlating with better outcomes and reduced breast cancer recurrence." (PMID 41295207, 2025). "In this study, we analyzed 4493 premenopausal women with early‐stage estrogen‐receptor breast cancer to see how taking tamoxifen with certain enzyme‐inhibiting drugs (CYP2D6, CYP2C19, and CYP3A4 inhibitors) affected the risk of cancer recurrence." (PMID 40364655, 2025). "The present study found no significant racial differences in terms of CYP2D6*5, CYP2C19*1, CYP2C19*3 and tamoxifen metabolism types among Han and Uygur premenopausal patients with breast cancer in Xinjiang." (PMID 38681733, 2024). "In this study, we assessed the effect of CYP2C19 genotypes on tamoxifen metabolism and efficacy in an extensive cohort of Caucasian breast cancer patients receiving tamoxifen as adjuvant endocrine therapy." (PMID 33432065, 2021). "Our aim was to investigate the effect of CYP2C19 genotypes on tamoxifen concentrations and metabolic ratios (MRs) and breast cancer recurrence in a large cohort of Caucasian women." (PMID 33432065, 2021). "Conversely, miR148a increases levels of CYP3A4 and CYP2C19 and is downregulated in a number of cancers, including most of the lower gastrointestinal (GI) tumors, along with head & neck cancers, breast cancer, lung cancer and melanoma." (PMID 31963461, 2020).
breast carcinoma (continued). "CYP2D6 have been intensively studied, but the role of CYP2C19 is less elucidated, and we studied the association of CYPC19 genotype and recurrence of breast cancer." (PMID 28798474, 2017). "Our results indicate that inherited changes in CYP2C19 gene participating in estrogen catabolism have an influence on the molecular subtype of breast cancer." (PMID 25466287, 2014). "CYP2C19 has also been reported to participate in tamoxifen metabolism during breast cancer treatment, as it contributes in tamoxifen 4-hydroxylation." (PMID 25466287, 2014). "The role of the CYP2C19 deletion allele, as well as that of the CDH19 deletion, in breast cancer predisposition warrants further studies and the obtained results should be replicated with larger and independent case–control cohorts." (PMID 25466287, 2014). "To this end, we have analyzed the occurrence of polymorphisms in three genes (ESR1, CYP2C19 and UGT2B15) that were earlier shown to have prognostic significance in tamoxifen-treated breast cancer patients." (PMID 23951298, 2013). "It has been shown that functional genetic variants of the CYP2C19 are associated with overall breast cancer risk and HRT-related breast cancer risk." (PMID 23226154, 2012). "This study investigated the susceptibility and prognostic implications of the CYP2E1, CYP2C19, CYP2D6, mEH and NAT2 gene polymorphisms in breast carcinoma patients." (PMID 18423013, 2008). "We measured the association between pharmaceutical inhibition of CYP2D6, CYP2C19, and CYP3A4 and recurrence in a large cohort of tamoxifen‐treated Danish premenopausal breast cancer patients using a Bayesian joint modeling approach and compared this with traditional Cox regression models." (PMID 40364655, 2025). "Conversely, individuals with low CYP2D6 activity and high CYP2C19 metabolism may experience shorter recurrence-free survival and breast cancer-specific survival, particularly among premenopausal women." (PMID 41295207, 2025). "The results of this study suggest that CYP2D6 and CYP2C19 genotypes need to be tested in patients with breast cancer to allow physicians to tailor the treatment according to these genotypes, thereby reducing mortality rates and personalising the treatment of patients with breast cancer." (PMID 38681733, 2024). "The aim of this study was to investigate the frequency distribution of the cytochrome P450 (CYP450) enzymes, CYP2D6 and CYP2C19, and the form of tamoxifen metabolisation in premenopausal patients with breast cancer in the Han and Uygur ethnic groups of Xinjiang to guide rational clinical drug use." (PMID 38681733, 2024). "They reported a 27.2% frequency for CYP2C19*2 in 67 breast cancer patients." (PMID 34308762, 2021). "CYP2C19 polymorphisms do not have a significant impact on tamoxifen metabolism or breast cancer relapse." (PMID 33432065, 2021). "Also, the relationship between CYP2C19 genotypes and breast cancer recurrence has been examined, yet contradictory results have also been published." (PMID 33432065, 2021). "CYP2B6 and CYP2C19 were previously reported as unfavorable prognosis markers in breast cancer." (PMID 34423049, 2021). "Their study demonstrated that elevated CYP2C19 leads to increased EET levels in a highly metastatic breast cancer cell line, LM6, and that using short hairpin RNA (shRNA) to silence CYP2C19 expression reduces EET levels and decreases the cell's metastatic potential." (PMID 32581794, 2020). "For instance, exogenous miR148a could be administered to boost its levels and effect on CYP3A4 and CYP2C19 in GI tumors, head & neck cancers, breast cancer, lung cancer and melanoma." (PMID 31963461, 2020). "In the present study, we investigated the pharmacokinetics profile and the influence of CYP2D6, CYP2C9, CYP2C19, CYP3A5, POR, ABCB1 and UGT2B15 polymorphisms on the plasma level of tamoxifen and its active metabolites in Ethiopian breast cancer patients receiving adjuvant tamoxifen." (PMID 31547390, 2019).
breast carcinoma (continued). "To obtain a more clinically relevant measure of protein expression levels, we randomly selected clinical paraffin-embedded tumor samples representative of all the breast cancer subtypes and subjected them to IHC analysis against CYP2C19/9, CYP2J2, CYP3A4 and sEH antibodies." (PMID 31072371, 2019). "Based on their biological functions and recurrence, two of the previously identified deletion alleles disrupting CYP2C19 and CDH19 genes, respectively, were hypothesized to play a role in breast cancer predisposition also in the general population." (PMID 25466287, 2014). "Here we have defined the exact breakpoints of six previously identified deletion alleles disrupting the CYP2C19, CDH19, CASP3, DCLRE1C, DAB2IP and ITGA9 genes, respectively, and evaluated their association with breast cancer risk and disease subtype using a Northern Finnish case–control cohort." (PMID 25466287, 2014). "No prognostic impact of CYP2C19*2 polymorphism in tamoxifen-treated breast cancer patients was also reported by other groups." (PMID 23951298, 2013). "Consistently, a study confirmed that enzymes including CYP1A1, CYP2C19, ABCB1, and other key transporters involved in drug resistance were significantly upregulated in the anthracycline-R breast cancer cell lines." (PMID 36551262, 2022). "This study confirmed the safety and feasibility of using the Inje cocktail to assess the in vivo activity of CYP2C9, CYP2C19, CYP2D6, and CYP3A4 in women receiving chemotherapy for breast cancer (BC)." (PMID 33707475, 2021). "Cyclophosphamide, the cornerstone of breast cancer chemotherapy in Ethiopia, is mainly metabolized to 4-hydroxy-cyclophosphamide by genetically polymorphic CYP3A, CYP2B6, CYP2C9, CYP2C19, and CYP2J2 enzymes." (PMID 31139078, 2019). "We observed a 2- to 10-fold increase in the gene expression of CYP2C19 and CYP2J2 in the triple negative mammary tumor tissues compared with the paired normal tissues." (PMID 31072371, 2019). "Here we examined relationships between the serum levels of tamoxifen, estrogens, follicle-stimulating hormone (FSH), and also determined the genotypes of CYP2C19, 2D6, 3A5, and SULT1A1 in 90 postmenopausal breast cancer patients." (PMID 20565970, 2010). "CYP2E1, CYP2C19, CYP2D6, mEH and NAT2 genotype frequencies in control subjects and in patients with breast carcinoma." (PMID 18423013, 2008). "Additionally, multifactor dimensionality reduction (MDR) revealed significant gene-gene interactions between CYP2C19 and CYP2B6, influencing treatment responses in breast cancer patients." (PMID 39598531, 2024). "Liu and colleagues showed that Norendox inhibited CYP2C19 and aromatase (CYP19A1) activity, while CYP19A1 activity was also inhibited by Endox pointing to a dualistic inhibitory effect of Endox on estrogen-driven breast cancer cells." (PMID 29285606, 2018). "Among our top ranking genes for predicted breast cancer drugs are CYP2A6, and CYP2C19." (PMID 22346740, 2012). "These previous findings are in accordance with ours which demonstrate the absence of any association between CYP2C19 and CYP2E1 gene polymorphisms with breast cancer." (PMID 18423013, 2008). "To conclude, we have shown that CYP2C19 polymorphisms have no or little impact on concentration levels and MRs of tamoxifen, endoxifen, 4-hydroxy-tamoxifen and NDM-tamoxifen, or clinical outcomes in breast cancer patients." (PMID 33432065, 2021). "Germ line DNA samples from 230 patients with breast cancer on AC therapy were genotyped for the following SNPs: ABCB1 C1236T, G2677T/A and C3435T, SLC22A16 A146G, T312C, T755C and T1226C, CYP2B6*2, *8, *9, *3, *4 and *5, CYP2C9*2 and *3, CYP3A5*3 and CYP2C19*2." (PMID 20179710, 2010).
breast carcinoma (continued). "Therefore, CYP2C19 genotypes might not be clinically decisive for patients with early-breast cancer treated with adjuvant tamoxifen." (PMID 33432065, 2021). "Other investigations have not observed a statistically significant effect on cyclophosphamide pharmacokinetics associated with the CYP2C19*2 SNP.Variants of the other CYP enzymes investigated in this study had no impact on outcome or toxicity in this cohort of breast cancer patients." (PMID 20179710, 2010).
acute coronary syndrome (43 papers, 2010 to 2025). Signs and symptoms related to acute ischemia of the myocardium secondary to coronary artery disease. "Testing for CYP2C19 metabolizer status prior to clopidogrel commencement for acute coronary syndrome patients, is supported by the American Heart Association and demonstrated to significantly decrease the risk of recurrent myocardial infarction." (PMID 40710411, 2025). "This study aimed to determine the effects of clinically significant gene variants of CYP2C19 on atorvastatin therapy in patients with acute coronary syndromes." (PMID 38791422, 2024). "The inhibition of CYP2C19, in patients with acute coronary syndrome, has been implicated in the occurrence of stent thrombosis and myocardial death." (PMID 35811736, 2022). "Polymorphisms of the CYP2C19 gene and clinical factors are strong predictors of cardiovascular outcomes for patients with acute coronary syndrome treated with oral clopidogrel." (PMID 34384383, 2021). "In the present study, in order to assess the potential association of CYP2C19 polymorphic alleles with platelet reactivity in acute coronary syndrome (ACS) patients, we studied the promoter, coding regions and intron-exon boundaries of the gene." (PMID 34065778, 2021). "Second, our analysis was limited to elective PCI patients only, while the correlation between platelet reactivity and CYP2C19 genotype with clinical outcome is stronger in high risk patients, for example after acute coronary syndrome (ACS)." (PMID 32932966, 2020). "The main objective of our study was to investigate the association of CYP2C19*2 and CYP2C19*3 loss-of-function and CYP2C19*17 gain-of-function variants of CYP2C19 gene with Clopidogrel resistance in a sample of Moroccan Acute Coronary Syndromes patients." (PMID 29347970, 2018). "used RWD on purchased prescription drugs, hospital discharge, death, and genotype for CYP2C19*2, CYP2C19*3, and CYP2C19*8 loss‐of‐function (LOF) variants from a cohort of prospective patients with acute coronary syndrome or symptomatic chronic coronary disease." (PMID 38752299, 2024). "In addition, the positive predictive value of CYP2C19 loss-of-function genetic polymorphisms is estimated to be between 12% and 20% in patients who have acute coronary syndrome (ACS) and are undergoing percutaneous coronary interventions (PCIs)." (PMID 23908855, 2013). "Our pioneering study describes the effect of the CYP2C19 phenotype on atorvastatin therapy in patients with acute coronary syndromes." (PMID 38791422, 2024). "According to the latest CPIC issued CYP2C19-clopidogrel recommendations, patients with intermediate CYP2C19 activity should avoid clopidogrel if they are using it for acute coronary syndrome (ACS) or following a percutaneous cardiac intervention (PCI)." (PMID 36154845, 2022). "We analyzed the coding and regulatory regions of CYP2C19 in 166 patients with acute coronary syndrome (ACS) treated with clopidogrel." (PMID 34065778, 2021). "CYP2C19 poor metabolizers were shown to exhibit higher cardiovascular event rates after acute coronary syndrome, or percutaneous coronary intervention, as compared to patients with normal CYP2C19 function." (PMID 32149610, 2020). "Since genetic testing is increasingly widespread, the Clinical Pharmacogenetics Implementation Consortium provided guidelines for clopidogrel therapy in acute coronary syndromes/PCI patients whose CYP2C19 genetic information is available." (PMID 26218263, 2015). "Laboratories are increasingly requested to perform CYP2C19 genetic testing when managing clopidogrel therapy, especially in patients with acute coronary syndrome undergoing percutaneous coronary intervention." (PMID 26218263, 2015). "Paths from two clinical characteristics (diabetes mellitus and acute coronary syndrome (ACS)) and two genetic variants (CYP2C19*2 and CYP2C19*17) independently predicted HTPR (path coefficients: 0.11 0.10, 0.17, and -0.10, respectively; p<0.05 for all)." (PMID 25051347, 2014).
acute coronary syndrome (continued). "The relationship between CYP2C19 genotype and platelet response to clopidogrel has been confirmed in a number of studies in patients (both Caucasian and Asian) with acute coronary syndrome or undergoing PCI." (PMID 27713279, 2010). "In addition, a genetic sub-study of the PLATO trial stated that another antiplatelet, ticagrelor, showed better efficacy in managing acute coronary syndromes than clopidogrel despite the CYP2C19 genotype." (PMID 40232632, 2025). "Evidence on the utility of CYP2C19 point-of-care (POC) testing to guide antiplatelet therapy selection in patients with acute coronary syndrome (ACS) or stable coronary artery disease (CAD) undergoing percutaneous coronary intervention (PCI) is currently limited." (PMID 41357895, 2025). "The objective of this study is to explore the relationships of the effects of CYP2C19 and PON1 Q192R polymorphism on the activity of clopidogrel and the risk of high platelet responsiveness (HPR) by thrombelastography in patients with acute coronary syndrome (ACS)." (PMID 31772608, 2019). "Ticagrelor was found to be more efficacious for acute coronary syndrome than clopidogrel, irrespective of CYP2C19 and ABCB1 polymorphisms." (PMID 23908855, 2013). "The CPIC guideline only recommended CYP2C19 genotype-guided prescription of clopidogrel in patients with acute coronary syndrome receiving anti-platelet therapy for percutaneous coronary intervention, therefore the projected impact of clopidogrel could be over-estimated." (PMID 33600428, 2021). "So far, only one study by Jiang and You examined the clinical and economic outcomes of CYP2C19 LOF- and GOF-guided antiplatelet therapy in subjects with acute coronary syndrome undergoing percutaneous coronary intervention." (PMID 29445720, 2017). "Patients with decreased CYP2C19 function because of genetic polymorphisms metabolize clopidogrel poorly and have higher rates of cardiovascular events after acute coronary syndrome (ACS) and percutaneous coronary interventions (PCIs) than patients with normal CYP2C19 function." (PMID 21423686, 2011). "In a third study, in patients with non-ST elevation acute coronary syndrome, a lower rate of non-responders was found among CYP2C19*17 carriers as compared to subjects not carrying this allele." (PMID 27713279, 2010). "Thus, acute coronary syndrome (ACS) patients with DM/obesity who have undergone PCI and are intermediate CYP2C19 metabolizers may yield better treatment outcomes if prescribed ticagrelor instead of clopidogrel." (PMID 35647265, 2022).